LMNA (lamin A/C)
Description:
[Lamin-A/C]: Lamins are intermediate filament proteins that assemble into a filamentous meshwork, and which constitute the major components of the nuclear lamina, a fibrous layer on the nucleoplasmic side of the inner nuclear membrane. Lamins provide a framework for the nuclear envelope, bridging the nuclear envelope and chromatin, thereby playing an important role in nuclear assembly, chromatin organization, nuclear membrane and telomere dynamics. Lamin A and C also regulate matrix stiffness by conferring nuclear mechanical properties. The structural integrity of the lamina is strictly controlled by the cell cycle, as seen by the disintegration and formation of the nuclear envelope in prophase and telophase, respectively. Lamin A and C are present in equal amounts in the lamina of mammals. Also involved in DNA repair: recruited by DNA repair proteins XRCC4 and IFFO1 to the DNA double-strand breaks (DSBs) to prevent chromosome translocation by immobilizing broken DNA ends. Required for normal development of peripheral nervous system and skeletal muscle and for muscle satellite cell proliferation. Required for osteoblastogenesis and bone formation. Also prevents fat infiltration of muscle and bone marrow, helping to maintain the volume and strength of skeletal muscle and bone. Required for cardiac homeostasis. [Prelamin-A/C]: Prelamin-A/C can accelerate smooth muscle cell senescence. It acts to disrupt mitosis and induce DNA damage in vascular smooth muscle cells (VSMCs), leading to mitotic failure, genomic instability, and premature senescence.
Synonyms: LMN1; HGPS; MADA; CDCD1; CDDC; CMD1A; CMT2B1; EMD2; FPL; FPLD; FPLD2; IDC; LDP1; LFP; LGMD1B; LMNC; LMNL1; PRO1
Tractability: Small molecule: a structure with a bound ligand is known; it belongs to a druggable protein family. PROTAC: UniProt records ubiquitination sites on it; ubiquitination databases record sites on it; its protein half-life has been measured; a small molecule that binds it is known.
Target class: Structural protein
Gene: Protein-coding gene on chromosome 1 (156,082,572 to 156,140,081, forward strand). Ensembl gene ENSG00000160789.
Subcellular location: Nucleus lamina; Nucleus envelope; Nucleus, nucleoplasm; Nucleus matrix; Nucleus speckle (Isoform C)
Subcellular location (Human Protein Atlas): Nuclear speckles
Pathways (Reactome):
Cell Cycle: Depolymerization of the Nuclear Lamina; Initiation of Nuclear Envelope (NE) Reformation; Nuclear Envelope Breakdown
Disease: Deregulated CDK5 triggers multiple neurodegenerative pathways in Alzheimer's disease models; Signaling by BRAF and RAF1 fusions
Cellular responses to stimuli: XBP1(S) activates chaperone genes
Programmed Cell Death: Breakdown of the nuclear lamina
Reproduction: Meiotic synapsis
Gene Ontology:
Molecular function: protein binding; structural constituent of cytoskeleton; structural constituent of nuclear lamina
Biological process: cellular response to hypoxia; cellular senescence; DNA double-strand break attachment to nuclear envelope; double-strand break repair via nonhomologous end joining; negative regulation of cell population proliferation; nuclear envelope organization; establishment or maintenance of microtubule cytoskeleton polarity; heterochromatin formation; negative regulation of cardiac muscle hypertrophy in response to stress; nuclear migration; nuclear pore localization; protein localization to nuclear envelope; protein localization to nucleus; regulation of cell migration
Cellular component: nuclear envelope; nuclear lamina; nuclear matrix; nuclear membrane; nuclear speck; nucleoplasm; nucleus; site of double-strand break; cytosol; lamin filament; nuclear lumen
Genetic constraint (gnomAD): Loss-of-function variants: 20 observed, 70.54 expected, observed/expected ratio (o/e) 0.28, 90% interval 0.2 to 0.41. The upper end of that interval is the gene's LOEUF score, 0.41, which puts it in group 1 of 6, group 1 being the genes least tolerant of losing a copy. Missense variants: 652 observed, 907.79 expected, observed/expected ratio (o/e) 0.72, 90% interval 0.67 to 0.77. Synonymous variants: 339 observed, 370.1 expected, observed/expected ratio (o/e) 0.92, 90% interval 0.84 to 1.
Gene-disease validity (ClinGen):
ClinGen rates the evidence that LMNA causes each of these diseases.
dilated cardiomyopathy 1A (autosomal dominant): Definitive.
lipodystrophy (semidominant): Definitive. A congenital or acquired disorder characterized by abnormal loss or redistribution of the adipose tissue in the body.
arrhythmogenic right ventricular cardiomyopathy (autosomal dominant): Limited.
Cancer hallmarks: genome instability and mutations (suppresses)
Homologues: Orthologues: chimpanzee LMNA (99% identical), macaque LMNA (99% identical), dog LMNA (98% identical), rabbit LMNA (98% identical), rat Lmna (97% identical), pig LMNA (97% identical), mouse Lmna (97% identical), guinea pig LMNA (91% identical), tropical clawed frog lmna (73% identical), zebrafish lmna (65% identical). Paralogues in human: LMNB1 (47% identical), LMNB2 (47% identical), KRT5 (20% identical), PRPH (19% identical), KRT8 (19% identical), NEFM (19% identical), KRT6B (19% identical), KRT18 (19% identical), KRT6A (19% identical), KRT6C (19% identical), KRT75 (19% identical), GFAP (18% identical), and 56 more.
Diseases named in the same sentence as LMNA in open-access papers:
LMNA is named in the same sentence as 287 diseases in open-access papers, as found by Europe PMC text mining. Sharing a sentence is not in itself a finding about the gene and the disease. The quoted sentences say what the papers report.
laminopathies (262 papers, 2007 to 2026). "Laminopathies are a group of rare disease due to mutations in the LMNA gene, which is crucial for nuclear integrity and cellular rigidity." (PMID 41667453, 2026). "Missense mutations in LMNA are linked to a spectrum of diseases known as laminopathies, which include conditions, such as dilated cardiomyopathy (DCM), muscular dystrophy, and progeria." (PMID 41688022, 2026). "Recent studies have connected sterile inflammation to laminopathies, a group of genetic disorders caused by mutations in the LMNA gene, which encodes nuclear intermediate filament proteins essential for nuclear structure and function." (PMID 40897109, 2025). "Genetic testing identified a heterozygous pathogenic variant in the LMNA gene (NM_170707.3.456_457insTCTC, NP_733821.1.Glu154GlnfsX2), classified as likely pathogenic and associated with laminopathy." (PMID 40927574, 2025). "Aberrations in Lamin A expression have been well-characterized, with over 400 distinct mutations of the LMNA gene linked to various mammalian diseases, termed laminopathies." (PMID 39827403, 2025). "Mutations in LMNA give rise to a wide spectrum of human diseases collectively known as laminopathies, demonstrating remarkable tissue specificity despite the ubiquitous expression of lamins A/C." (PMID 41357091, 2025). "Mutations in the human LMNA (fly LamC) gene cause laminopathies, including cardiomyopathies characterized by arrhythmias and heart failure." (PMID 40099194, 2025). "Hundreds of LMNA variants cause laminopathies, which manifest in diverse phenotypes, including premature aging and different forms of cardiomyopathy, muscular dystrophy, lipodystrophy, and neurodegenerative disorders." (PMID 40783787, 2025). "Lamin A/C is a crucial component of the nuclear envelope with Lamin A/C deficiency causing laminopathies, increased DNA damage, and defective mechanotransduction." (PMID 40923769, 2025). "Specifically, mutations in the LMNA gene that encodes A-type nuclear lamins (lamin A/C) cause a heterogeneous group of diseases (“laminopathies”) with high prevalence of cardiomyopathies 6–8." (PMID 38948795, 2025). "Variations in LMNA gene are linked to laminopathies, which affect muscles, fat, and bones, causing skeletal deformities, including scoliosis, providing a mechanistic link between nuclear envelope dysfunction and spinal deformity." (PMID 41210864, 2025). "Overlapping but distinct phenotypes have been noted in ZMPSTE24 deficiency and other laminopathies caused by LMNA pathogenic variants, such as Emery-Dreifuss muscular dystrophy." (PMID 40644604, 2025). "Our findings suggest that the LMNA p.(Glu105Leu) variant significantly affects cellular organization and energy metabolism in cardiomyocytes, potentially contributing to laminopathy-associated cardiac dysfunction." (PMID 40610603, 2025). "Even more intriguing is the observation that, differently from laminopathies, mutations, deletions, or copy‐number changes in the LMNA gene are rare in most human cancers." (PMID 39866838, 2025). "Pathogenic variants in the LMNA gene cause a broad spectrum of hereditary diseases called laminopathies." (PMID 39940784, 2025). "Specifically, mutations in LMNA (encoding lamin A/C) cause a heterogeneous group of diseases (‘laminopathies’) that often include cardiomyopathy." (PMID 41073815, 2025). "Laminopathies are a broad spectrum of hereditary diseases caused by pathogenic variants of the LMNA gene." (PMID 39940784, 2025). "The LMNA gene, the most commonpathogenic gene responsible for laminopathies, harbors variants that can lead todiverse clinical phenotypes, such as progeroid syndromes, lipodystrophies,muscular dystrophies, and cardiomyopathies." (PMID 40704756, 2025).
laminopathies (continued). "Since the discovery of the LMNA gene, variants in which cause laminopathies, over 1000 scientific and clinical studies have been published." (PMID 39940784, 2025). "Parental mosaicism for LMNA variants has been previously reported across distinct laminopathy phenotypes." (PMID 41300702, 2025). "Among these, mutations in lamin-encoding genes result in a broad but rare category of diseases referred to as laminopathies – majority of which have been linked to mutations in LMNA." (PMID 39943681, 2025). "Today, hundreds of likely pathogenic variants in the LMNA gene have been described, and have been associated with a spectrum of diseases, referred to as laminopathies, which affect muscle, heart, fat distribution and metabolic processes." (PMID 40610603, 2025). "Mutations in LMNA are implicated in a range of conditions known as laminopathies, which exhibit diverse phenotypes encompassing disorders affecting muscles, axonal neurons, progeroid syndromes, and lipodystrophies." (PMID 38887266, 2024). "Laminopathies are inherited diseases resulting from abnormalities in A-type lamins due to variants in the LMNA gene or in other genes involved in prelamin A processing." (PMID 39273270, 2024). "Research on laminopathies has highlighted how LMNA mutations disrupt adipose tissue function and metabolic regulation, leading to altered fat distribution and metabolic pathway dysfunctions." (PMID 39125589, 2024). "Our model has implications for laminopathies, a class of diseases marked by mutations in the gene encoding lamin A (LMNA), as well as for diseases marked by changes in local tissue stiffness." (PMID 39140137, 2024). "Pathogenic gene variants in the LMNA gene cause a group of heterogeneous human diseases collectively termed laminopathies." (PMID 39669119, 2024). "The mutations in the LMNA gene cause a group of rare genetic disorders collectively called laminopathies." (PMID 39542246, 2024). "Although FPLD is typically attributed to single causative mutations, combined alterations such as those found in patients with compound heterozygous mutations in the LMNA gene, underscore the complex genotype/phenotype relationships in laminopathies." (PMID 39669119, 2024). "In fact, the phenomenon was first comprehensively described in laminopathy patient fibroblasts with different mutations in the LMNA gene and later also confirmed in cells that completely lack A-type or B-type lamins." (PMID 38485766, 2024). "Despite LMNA expression in most differentiated cells, LMNA mutations primarily affect mesoderm-derived lineages in diseases collectively called laminopathies." (PMID 39273049, 2024). "Reported literature from Pakistani cohorts discusses the LMNA gene related to premature aging, while we report a novel variant which expands phenotypic expression of the laminopathies by the addition of neurological manifestations, lipodystrophy and hypotonia." (PMID 39767643, 2024). "Most laminopathies result from dysfunctional variants of LMNA, whereas a few have been linked to variants of LMNB1 and LMNB2." (PMID 38261271, 2024). "Mutations in the LMNA gene lead to a spectrum of diseases called laminopathies, which include muscular dystrophies, cardiomyopathies, lipodystrophies, and premature aging syndromes such as progeria." (PMID 39125589, 2024). "This study identified lamin A/C-associated proteomes from two native tissues, heart and skeletal muscle, often perturbed in laminopathy and frailty." (PMID 37936983, 2023). "Some laminopathy mutations appear to destabilize the lamin A/C proteins, such as the cardiomyopathy-linked S143P and ΔK32 mutations, which undergo increased poly-ubiquitination and accelerated turnover." (PMID 37619289, 2023). "Mutations in the gene for lamin A/C (LMNA) cause a diverse range of diseases known as laminopathies." (PMID 36899919, 2023).
laminopathies (continued). "LMNA gene encodes lamin A/C protein which participates in the construction of nuclear lamina, the mutations of LMNA result in a wide variety of diseases known as laminopathies." (PMID 37784143, 2023). "Mutations in LMNA, the gene encoding A-type lamins, cause laminopathies-diseases of striated muscle and other tissues." (PMID 35925868, 2023). "To date, over 600 disease-causing rare LMNA variants are characterized, and these “laminopathies” are associated with heterogeneous clinical phenotypes, including neuromuscular, cardiac, and metabolic disorders." (PMID 36968203, 2023). "Mutations to the LMNA gene cause laminopathies including Hutchinson-Gilford progeria syndrome (HGPS) that severely affect the cardiovascular system." (PMID 37162946, 2023). "HGPS is a laminopathy, one of a set of diseases caused by mutations in the lamin A (LMNA) gene or genes that encode for proteins involved in lamin processing." (PMID 37354210, 2023). "Models that recapitulate both tauopathy and laminopathy features have been built upon mutations in LMNA." (PMID 37013265, 2023). "Over 400 mutations in LMNA have been linked to diseases collectively called laminopathies, the majority affecting muscle." (PMID 37190051, 2023). "Meanwhile, laminopathies are mainly caused by mutations in the LMNA gene and manifest nuclear architecture disruption." (PMID 37884611, 2023). "Progeria laminopathy is caused by a point mutation at LMNA gene, which results in an alternatively spliced isoform called Progerin that produces nuclear instability and premature aging." (PMID 39872108, 2023). "Pathogenic variants of the human LMNA gene contribute to a broad spectrum of tissue-specific diseases that are collectively referred to as laminopathies." (PMID 37624850, 2023). "Mutations in the human lamin A/C gene (LMNA) cause at least eleven different human diseases called laminopathies, with Hutchinson–Gilford progeria syndrome (HGPS) as a prominent example." (PMID 37987370, 2023). "Mutations in the LMNA gene cause a collection of diseases known as laminopathies, including muscular dystrophies, lipodystrophies, and early-onset aging syndromes." (PMID 37190051, 2023). "Our goal is to characterize laminopathy-associated missense variants of human LMNA in order to accelerate phenotypic evaluation of known pathogenic variants and emergent VUS." (PMID 37624850, 2023). "Mutations in LMNA have been reported to cause a variety of clinical phenotypes, collectively known as laminopathies." (PMID 36357925, 2022). "Mutations in the LMNA gene or alterations in its expression levels have been linked to a variety of diseases called laminopathies, and to some extent, cancer progression." (PMID 36111332, 2022). "Model of mutant LMNA‐mediated induction of nuclear proteotoxicity and DNA damage and its impact on the onset of laminopathy‐associated progeria." (PMID 36225129, 2022). "Laminopathies, a group of pathologies caused by mutations in the gene encoding Lamin A/C (LMNA), are characterized by rapid aging, higher incidence of atherosclerosis, and premature death caused by cardiovascular dysfunction including heart attack and strokes." (PMID 35784481, 2022). "More than 450 distinct mutations have been identified on the human LMNA gene, and the hallmark of laminopathies is the presence of nuclear abnormalities, including herniations, honeycomb-structures, and donut-like nuclei." (PMID 35883635, 2022). "A majority of laminopathies are associated with heterozygous LMNA mutations, which include mostly missense and a smaller fraction of nonsense mutations that span the gene." (PMID 36503349, 2022). "Mutations in the LMNA gene are the main cause of laminopathies, a spectrum of distinct genetic diseases attributable to mutations or altered post-translational processing of the nuclear envelope/lamina proteins." (PMID 35656549, 2022).